ABCA4 (ATP binding cassette subfamily A member 4)
Diseases named in the same sentence as ABCA4 in open-access papers (continued):
Sharing a sentence is not in itself a finding about the gene and the disease.
retinopathy (continued). "Several approaches have been brought forward to predict progression in patients with ABCA4-related retinopathy." (PMID 32751377, 2020). "The assessment of ABCA4-related retinopathy with this technology revealed that flecks are heterogeneous in terms of fluorescence emission." (PMID 32726903, 2020). "The study included a total of 311 eyes of 156 patients (101 female) with ABCA4-related retinopathy (mean age 38.77 years, total range 9.43–86.12 years) and 108 eyes of 54 controls (35 female, mean age 39.24 years, total range 13.14–77.02 years)." (PMID 32751377, 2020). "Previous studies for ABCA4-related retinopathy that investigated the evidence for structure–function correlations between retinal sensitivity and multimodal imaging only used a limited number of narrowly selected predictors and/or application of linear models." (PMID 32751377, 2020). "Using an ensemble ML approach, different statistical perspectives were combined to increase the robustness of the demography- and morphology-based functional prediction (inferred retinal function) in ABCA4-related retinopathy." (PMID 32751377, 2020). "This device has allowed a better characterization of the green-emitting fluorophores in healthy eyes, atrophic AMD, ABCA4-related retinopathy, and optic disc drusen." (PMID 33375699, 2020). "This proband harbors another ABCA4 change, c.1928G > T and has bilateral macular atrophy and yellow-white retinal lesions (flecks), a phenotype suggestive of ABCA4-retinopathy." (PMID 27628848, 2016). "ABCA4 related retinopathies include an interesting diversity of common and unusual retinal phenotypes." (PMID 24444108, 2014). "The presence of fibrotic scarring in the paramacular area, the dark choroid, the autofluorescence phenotype and the ERG results are consistent with an ABCA4 related retinopathy." (PMID 24444108, 2014). "Herein, I provide a review of the latest advancements in precision medicine for ABCA4 retinopathy, specifically on the applications of gene, drug, and stem cell therapies, offering insights into the path forward as we seek to transform the lives of those living with this retinal disorder." (PMID 39060921, 2024). "We envision that this platform could serve as a primary screen for more sophisticated in vitro testing, enabling the discovery of breakthrough agents to rescue ABCA4 protein defects and mitigate ABCA4-related retinopathy." (PMID 38674104, 2024). "Clinical characteristics of ABCA4 retinopathy probands with c.6480-35A>G." (PMID 37779911, 2023). "To date, there are no FDA-approved therapies for ABCA4-associated retinopathy, but several experimental treatments are being studied." (PMID 37779911, 2023). "ICD-10 code data indicated that 2 of the 187 p.Asn1868Ile homozygotes may have ABCA4 retinopathy; however, a more thorough and comprehensive assessment of OCT scans is required to accurately determine the specific macular condition these cases have." (PMID 37342033, 2023). "Interventions that increase stimulation of this pathway may improve RPE clearance of lipofuscin, which has the potential to decrease ABCA4 retinopathy disease progression by decreasing lipofuscin accumulation, thus slowing RPE and photoreceptor degeneration." (PMID 37834872, 2023). "International standard ERGs in 597 cases of ABCA4 retinopathy were classified into three functional phenotypes by human experts: macular dysfunction alone (group 1), or with additional generalized cone dysfunction (group 2), or both cone and rod dysfunction (group 3)." (PMID 36178783, 2022). "We propose progression of photoreceptor loss in the retina immediately surrounding the area of EZ-loss represents a measure of the leading front of the disease and, as such, may prove a valuable outcome measure for clinical trials of ABCA4-related retinopathy." (PMID 35076026, 2022). "Emixustat is currently being evaluated as a potential treatment in ABCA4-related retinopathy." (PMID 35739983, 2022).
retinopathy (continued). "As a step toward a unified measure of disease progression in ABCA4-related retinopathy that could apply to human and animal models, thinning the outer nuclear layer may be a potential candidate." (PMID 35076026, 2022). "DHA metabolism is believed to be altered in retinopathies, due to pathogenic mutations in ABCA4, although no positive results have been found in patients treated with DHA supplements." (PMID 35739983, 2022). "Imbalance in ERG phenotypic groups within our ABCA4 retinopathy cohort and diversity in genetic background may also impact generalizability through the potential for overfitting on small subpopulations." (PMID 36178783, 2022). "Thus, DNA base editors provide an exciting opportunity to correct this large proportion of pathogenic mutations and therefore provide therapeutic benefits for Stargardt and other ABCA4-retinopathy patients." (PMID 35154257, 2021). "Interestingly, gender disbalance was recently also reported in ABCA4-retinopathy, an autosomal recessive disease—where there were significantly more females with mild alleles in the patient cohort." (PMID 33669941, 2021). "The phenotype in ABCA4 retinopathies (ABCA4R) is highly variable." (PMID 34440414, 2021). "Interestingly, a tendency towards negative refractive errors has been previously reported in the setting of ABCA4-related retinopathy." (PMID 32751377, 2020). "While the diagnoses of the two unrelated parents (IV.3, IV.4), with autosomal dominant RP and autosomal recessive ABCA4-related retinopathy, respectively, were straight forward, the different molecular genetic findings of the two children (V.1, V.2) were rather unexpected." (PMID 32013026, 2020). "Given its relatively high prevalence as well as its disease course,ABCA4-associated retinopathy is an attractive target fortherapeutic intervention, yet no approved therapy exists." (PMID 32278709, 2020). "We, therefore, utilized ML approaches to explore the potential to predict ERG results, the grade of visual impairment, and best corrected visual acuity (BCVA) in ABCA4-related retinopathy based on patients’ demographic factors and structural data of the retina." (PMID 32751377, 2020). "Finding these,non-ABCA4, modifiers, genetic or non-genetic in nature, whichinfluence the expression of ABCA4-associated retinopathy in asubset of the cases, remains an important task." (PMID 32278709, 2020). "Apart from substantiating the functional relevance of structural alterations in ABCA4-related retinopathy, these novel calculated parameters may serve as quasi-functional surrogate markers in patient assessment and future clinical trials." (PMID 32751377, 2020). "In a recent study we investigated a cohort of cases where phenotypes wereconsistent with ABCA4-associated retinopathy but no disease-causingvariants were found in ABCA4 even after complete locus sequencing." (PMID 32278709, 2020). "In conclusion, a consistent structure–function relationship in ABCA4-related retinopathy could be demonstrated." (PMID 32751377, 2020). "Together, the various compounds that have been tested so far insubjects with ABCA4-associated retinopathy overall can beconsidered safe, yet none of them succeeded to demonstrate a hightherapeutic effect." (PMID 32278709, 2020). "After the discovery that this compoundcould remove lipofuscin from the RPE in monkeys, its potential forthe treatment of ABCA4-associated retinopathy is now alsobeing studied, with no data reported so far." (PMID 32278709, 2020). "Even if a more stringent definition (i.e., only patients with proven biallelic pathogenic mutation) would be more certain, the commonly accepted and here-used definition of ABCA4-related retinopathy is currently the best tradeoff between cohort size and limitations of genetic testing." (PMID 32751377, 2020).
retinopathy (continued). "Herein, we present a series of patients with molecularly confirmed ABCA4-associated retinopathy without macular atrophy in which detailed retinal imaging and functional testing have provided new insights into the earliest stages of disease." (PMID 29310964, 2018). "Children with a clinical and molecular diagnosis of ABCA4-associated retinopathy without evidence of macular atrophy." (PMID 29310964, 2018). "It is possible that sex may act as a modifier for certain genetic variants and not for others (the previous study of ABCA4-retinopathy highlighted sex imbalances for milder variants and not for patients with severe bi-allelic variants)." (PMID 40879293, 2025). "Moreover, a large study focusing on ABCA4 has shown that sequencing the entire locus (including the intronic regions) allowed the identification of a molecular diagnosis in 42.5% of the probands with suspected ABCA4-related retinopathy." (PMID 37107692, 2023). "However, late-onset ABCA4 retinopathy is diagnosed after the age of 45." (PMID 37342033, 2023). "Therefore we cannot exclude that these patients with monoallelic variants include some unconfirmed ABCA4-retinopathy (due to lack of deep ABCA4 sequencing or MLPA analysis), possibly some ARMD, or even that the genetic cause is to be found elsewhere." (PMID 35260635, 2022). "Therefore, mitigation of RPE local complement dynamics may slow disease progression in ABCA4-mediated retinopathies." (PMID 36359858, 2022). "Since ABCA4 is the major gene for both diseases, these could be classified as ABCA4-retinopathies." (PMID 35260635, 2022). "Despite its worldwide occurrence, the prevalenceof ABCA4-associated retinopathy is not yet known." (PMID 32278709, 2020). "Similar to recent studies (e.g., multicenter PROGSTAR study), the diagnosis of ABCA4-related retinopathy was based on a compatible phenotype and the presence of at least one disease-causing mutation in ABCA4 as well as the absence of mutations in Peripherin-2 (PRPH2)." (PMID 32751377, 2020). "Eight children with ABCA4-associated retinopathy without macular atrophy were identified." (PMID 29310964, 2018). "ABCA4 and RPE65 have also been proposed as genetic modifiers that result in a more severe phenotype in PRPH2 retinopathy." (PMID 41009962, 2025). "However, they would not explain the large differences ofexpression of ABCA4-associated retinopathy within families, inwhich trans-modifiers may play a larger role." (PMID 32278709, 2020). "Seventy-five subjects with IRD or no ocular diseases have been ascertained from the database of Japan Eye Genetics Consortium; 10 ABCA4 retinopathy, 20 RP1L1 retinopathy, 28 EYS retinopathy, and 17 normal patients/subjects." (PMID 31093368, 2019). "Combing electrophysiological analyses with genetic data can be powerful, not just in the field of rare diseases such as ABCA4-retinopathy, but also in interrogating effects of common genetic variants on retinal function." (PMID 36928229, 2023). "These are currently under investigation for other IRD genes such as ABCA4 and if successful, might also prove useful for CERKL retinopathy." (PMID 37331655, 2023). "It has been established that BCVA (as well as ‘inferred BCVA’) does not constitute an optimal endpoint in ABCA4-related retinopathy due to its high interindividual variability and the phenomenon of foveal non-involvement." (PMID 32751377, 2020). "To date, ML applications for prediction of function in ABCA4-related retinopathy have not been explored." (PMID 32751377, 2020). "Nevertheless, the concept of regional “sparing” is not entirely foreign to ABCA4 retinopathy." (PMID 41458191, 2026). "The purpose of this study is to determine whether the p.Asn1868Ile allele is associated with any subclinical pathogenic effects in the macula within the general population that do not have ABCA4 retinopathy, using a large population-based cohort." (PMID 37342033, 2023).
retinopathy (continued). "Notably, prediction accuracies may not necessarily translate to AMD as the ABCA4-related retinopathy cohort is a hereditary, monogenetic disease with rather well-defined ERG changes, while ERG findings in AMD are known to be much less specific." (PMID 33767409, 2021).
cancer (45 papers, 2010 to 2026). A tumor composed of atypical neoplastic, often pleomorphic cells that invade other tissues. "Within the list of top differentially expressed genes, in the UCHL1 KDs we found downregulation of the Wnt targets POSTN, SP7, and DLL1, of the transporter ABCA4, of the homeobox gene DLX4, and of genes recently linked to cancer progression ACTA2, AQ4, GRAP2, and ALK." (PMID 28472177, 2017). "Some selected genes with high discriminative ability, belonging to three cancer-relevant pathways, such as ATP-binding cassette (ABC) family of genes (ABCA4, ABCA8) were identified as prospective gene markers of lung AC other one (ABCB1, ABCC3 and ABCF2) should be also under serious consideration." (PMID 22369099, 2011).
tumor (10 papers, 2015 to 2024). "Among them, NXPH4 and ABCA4, as the genes with the heaviest regression coefficient, both suggest a worse prognosis, and NXPH4 is also significantly increased in MIBC tumor tissues." (PMID 36245981, 2022).
genetic diseases (6 papers, 2008 to 2023). "Altogether, this has greatly expanded our understanding ofcomplexity not only of the diseases caused by ABCA4 mutations,but of all Mendelian diseases in general." (PMID 32278709, 2020). "In addition to ABCA4, there are many other genes that lead to frequent genetic diseases but exceed the capacity of AAVs." (PMID 37852949, 2023).
eye disorder (2 papers, 2022 to 2025). A non-neoplastic or neoplastic disorder that affects the eye. "ABCA4-related retinopathy is the most common monogenic eye disorder in the world and is currently untreatable." (PMID 40693713, 2025).
autosomal recessive disease (1 paper, 2022). Autosomal recessive form of disease. "These and other mild ABCA4 alleles, including p.(Gly1961Glu) and the frequent hypomorph p.(Asn1868Ile), also exhibit some collective characteristics that are inconsistent with most autosomal-recessive diseases." (PMID 34874912, 2022).
ABCA4 also shares sentences with these, for which no sentence is quoted: cone dystrophy (8 papers); cystic fibrosis (6); infection (6); atherosclerosis (5); Pseudoxanthoma elasticum (5); retinitis pigmentosa 19 (5); choroideremia (4); cone-rod dystrophy 3 (4); neurodegenerative disease (4); pancreatic cancer (4); prostate carcinoma (4); adrenoleukodystrophy (3); Chorioretinal atrophy (3); hearing loss (3); melanoma (3); bladder cancer (2); deafness (2); diabetes (2); frontotemporal dementia (2); gastric cancer (2); glioblastoma (2); Hydrocephalus (2); neuroblastoma (2); oculocutaneous albinism (2); recessive retinal pigmentosa (2); Type 1 Usher syndrome (2); Usher syndrome type 1B (2); Aicardi-Goutieres syndrome (1); aniridia (1); ataxia (1).
A further 93 diseases each share a sentence with ABCA4 in 1 paper.